IL6 (interleukin 6)
Diseases named in the same sentence as IL6 in open-access papers (continued):
Sharing a sentence is not in itself a finding about the gene and the disease.
influenza (continued). "This suggested IL-6 as a marker of severe influenza H1N1pdm disease but not a potential therapeutic target which has important implications on the design and administration of influenza A therapeutics." (PMID 22679491, 2012). "Higher IL-6 and IFN-α levels have been reported in patients with influenza-associated febrile seizures compared to those without febrile seizures." (PMID 21989210, 2011). "Excessive cytokines (IL-6, TNF-a and IFN-γ), or elevated cytokine (IL-6, IL-12, and IFN-γ) levels have been observed in community acquired acute seasonal influenza A illness, or in severe seasonal influenza patients." (PMID 22174866, 2011). "To further investigate the effect of rm-APC treatment on the inflammatory response in severe influenza, we determined pulmonary levels of various cytokines (TNF-α, IL-1β, IL-6, IL-10, IL-12p70, IFN-γ) and chemokines (KC, MIP-2) in lung homogenates obtained 48 and 96 hours after infection." (PMID 20398279, 2010). "Our findings do however support the premise that the major target of IL-6 activity in our influenza model is the Treg population rather than conventional CD4+ T cells." (PMID 18389078, 2008). "We found that the activity of a subset of influenza-specific memory T cells (CD4+ T cells) was diminished in the absence of IL-6 due to the inhibitory effects of regulatory T cells—an effect that compromised protective anti-viral immunity." (PMID 18389078, 2008). "It was shown earlier, that proinflammatory cytokines (IL-1β, IL-6, TNF-α, IFN-α) and microglial reactivity were increased, while neurotrophic (BDNF, NGF) and immunomodulatory (CD200, CX3CL1) factors were decreased in the hippocampus of influenza infected adult mice." (PMID 41567998, 2025). "Interestingly, a recent study has proposed that IL-6 primarily contributes to defense against influenza by promoting protective antibody responses, rather than by mediating innate inflammation." (PMID 40692679, 2025). "While IL-6 and TGF-β1 were significantly elevated in MASLD patients with typical bacterial sCAP at admission, in MASLD patients with L. pneumophila, M. pneumoniae and influenza sCAP we observed a sharp early increase and a significant decline in IL-17A five days later." (PMID 40869413, 2025). "Interestingly, IL‐6 deletion did not exacerbate post‐influenza MRSA pneumonia like it has done in prior published studies of singular influenza infection or post‐influenza streptococcal pneumonia." (PMID 39921246, 2025). "Similarly, IL-6 plays an important role in the cytokine storm via the JAK2/STAT3 pathway in viral and bacterial pneumonia and is a predictive marker of inflammation indicative for a poor prognosis of influenza patients." (PMID 38791439, 2024). "Influenza may also influence the development of affective disorders in adults through cytokines released during the immune response, such as interferons, TNF-α, IL-1β, and IL-6, which activate the kynurenine pathway, producing neurotoxic metabolites." (PMID 39206043, 2024). "Unlike after adenovirus or influenza infections, AM from lungs that have recovered from pneumococcal pneumonia do not demonstrate elevated Cxcl2 or Il6 expression, whether of embryonic or adult HSC origin." (PMID 35133985, 2022). "The human cytokine profile was examined after immunization with trivalent influenza vaccine, and IP-10 and IFN-γ were detected at 7 h, with a peak response between 16 and 24 h after immunization, demonstrating distinct early cytokine profiles of IL-6 and other cytokines in subjects with myalgias." (PMID 36016227, 2022). "It has been reported that in older adults who had no subjective depressive symptoms, there was no change in plasma IL-6 concentrations after influenza vaccination, but in older adults with depressive symptoms, plasma IL-6 concentrations increased after vaccination." (PMID 35887537, 2022).
influenza (continued). "Moreover, even in co-infection experiments using different stimuli, as well as non-influenza (non-flu) or influenza A (flu) viruses, only very minor IL-6 production was induced." (PMID 34122407, 2021). "In this study, we observed that B.dorei administration decreased production of several cytokines (IL-1β, IL-6, IL-10,TNF-α, MCP-1, and IP-10) in lung and serum induced by influenza infection, which may alleviate excessive inflammatory response and ameliorate immunopathologic damage." (PMID 35154087, 2021). "Similarly, rfhSP-D has been shown to neutralize and downregulate pro-inflammatory cytokines in vitro including TNF-α, interferon (IFN)-α, IFN-β, interleukin (IL)-6, and regulated on activation normal T-cell expressed and secreted (RANTES), upon influenza infection of a basal epithelial cell line." (PMID 33542724, 2020). "While Il6 and Ifnγ expression were increased with influenza infection, regardless of vaccination status and viral burden, transcripts of Il6 were not significantly changed in NK cell depleted mice, while Ifnγ showed a trend for a decrease in NK cell depleted mice." (PMID 32117282, 2020). "Thus, during intranasal influenza immunization of infants, IL-6 does not seem to promote the recruitment of lymphocytes, but is important in a sustained memory T cell response." (PMID 33193346, 2020). "Notably, IL8, IL6, MCP1, and GCSF have been associated with ARDS, mortality and organ dysfunction in critically ill patients without influenza infection." (PMID 29163498, 2017). "Although the role of IL-6 in influenza pathogenesis has been documented, to date no studies have investigated its role in modulating lung repair responses necessary for recovery from influenza." (PMID 28262742, 2017). "Since this effect of IL-2/IL-6 supplementation can be reproduced with the addition of Toll-like receptor agonists, it may be possible to exploit this mechanism and design new vaccines to improve the CD8 T cell response to influenza vaccination in older adults." (PMID 27322555, 2016). "In addition, IL-6 is known to activate both STAT 3 and IL-23R expression, which could potentially play a role in IL-17 expression during influenza and S. aureus infection." (PMID 25651926, 2015). "Whilst influenza infection increased the production of pro-inflammatory cytokines and chemokines, as with RSV infection, treatment with vitamin D either before or after influenza infection decreased gene expression of TNF-α, IFN-β, ISG15, CXCL8, IL-6 and RANTES (CCL5)." (PMID 26035247, 2015). "However, IL-6 secretion from LPS-stimulated PBMCs was significantly higher in participants with self-reported cold or flu symptoms compared to participants without cold or flu symptoms in the past month (p = 0.0471)." (PMID 25788896, 2015). "Furthermore, recent data using a mouse model of influenza infection indicate that mice lacking IL-6 are less likely to survive the infection thereby implying a beneficial effect of IL-6 in controlling the infection." (PMID 24893655, 2014). "A relationship between functional ability in older people and the immune system has been documented in several studies: frail elderly individuals have higher CMV titers, elevated IL-6 and lower responses to influenza vaccination, but the interrelations between these are not clear." (PMID 23114110, 2012). "However, it is interesting that the four pro-inflammatory cytokines induced by Pam2-ODN 4 h after treatment (IL-1α, IL-1β, IL-6, and TNF) are also the first four pro-inflammatory cytokines induced from respiratory epithelial cells in native influenza infections." (PMID 22299046, 2012). "Elevated proinflammatory cytokines, particularly IL-6, predicted ICU admission (adjusted OR 12.6, 95%CI 2.6–61.5, per log10unit increase; P = 0.002), and correlated with fever, tachypnoea, deoxygenation, and length-of-stay (Spearman's rho, P-values<0.01) in influenza infections." (PMID 22022504, 2011).
influenza (continued). "To more closely examine the responsiveness of Tregs in IL-6−/− mice, we performed suppression assays designed to compare 1) Treg activity following polyclonal stimulation of the cells using CD3-specific mAbs and 2) influenza-specific Treg activity in both groups of mice." (PMID 18389078, 2008). "In addition to producing antibodies, B cells secrete pro-inflammatory cytokines such as IL-6, B cell activating factor, and a proliferation-inducing ligand, which can damage endothelial integrity and impair organ function in severe viral infections like EBOV, influenza, and SARS-CoV-2." (PMID 39676169, 2024). "In conclusion, our study suggested that TLR4, CD14, MyD88, NF-κB p65, HIF1 α, VEGF, IL17A, and IL6 in the TLR4/NF-κB p65 signaling pathway and HIF-1α/IL17 signaling pathway may be the key targets for the identified active compounds of HSSD to treat influenza by inhibiting inflammatory responses." (PMID 36386710, 2022). "To determine whether the mounted immune responses in the absence of IL-6 can confer protection from subsequent exposure to influenza, we immunized WT and IL-6 knockout mice with 10 μg of PR8 HA mRNA-LNP and 14 days later exposed them to a lethal dose of PR8 influenza virus." (PMID 35073387, 2022). "Also, the vaccination of 1 day old chickens with adenovirus vectored H5 and H7 influenza vaccine could induce IgA response in lachrymal fluid and increased interleukin-6 expression without inducing detectable levels of serum antibodies." (PMID 29624615, 2018). "Therefore, the lower plasma levels of IL-6 in post-menopausal women receiving ET could potentially result in better outcomes after influenza infection compared to post-menopausal women not receiving HT." (PMID 26859566, 2016). "Influenza infection induced expression of primary miRNAs rather than enhancing precursor miRNA processing and the changes in expression were far more potent than those triggered by anti-viral molecules such as interferons, interleukin-6 and TNFα in human respiratory cells." (PMID 24116168, 2013). "Inhibition by lefamulin as early as on Day 3 (but not on Day 6) correlates with reduced IL-6 and TNF-α levels and seems to be related to the reduction in influenza progression and pro-inflammatory response." (PMID 38791439, 2024). "In mice with influenza infection, medicinal inhibition of COX2 by celecoxib reduces TNF-α, granulocyte colony-stimulating factor, and IL-6 levels in bronchoalveolar lavage fluid without a substantial increase in viral titers." (PMID 36671699, 2022). "We found that TNF, IL-6, and MCP-1 were not significantly different in Tpl2-inhibited influenza-infected cells compared to vehicle-treated influenza-infected controls." (PMID 35051238, 2022). "LPS administration 4 days after influenza infection resulted in a synergistic increase in TNF-α, IL-1β, and IL-6 concentrations in lung tissue, but not in plasma." (PMID 29978355, 2018). "This neutrophil dependence for IL-1β release was not seen with other cytokines, with BALF IL-6 and TNF-α levels comparable between influenza-infected control and neutrophil-depleted mice." (PMID 29079611, 2018). "Given the strong correlation between increased BALF IL-6 and absence of ALI in influenza-infected HETs, the aim of this study was to define the source of this cytokine and its contribution to protection from ALI in HETs." (PMID 25840995, 2015). "Our study suggests that IL‐6 and JAK inhibition during influenza infection may not lead to improved pathogen clearance or limit tissue injury, in contrast to what has been observed in SARS‐CoV‐2 infection in humans." (PMID 39921246, 2025). "Hence, the influenza-induced alteration in cDC differentiation is independent of IFN-γ, type I IFNs, TNF-α, and IL-6." (PMID 30372491, 2018). "However, unlike IL-6 and TNF, the fulminant influenza infections observed in untreated mice actually induce 4-fold higher levels of interferon γ than the NTHi lysate treatment." (PMID 19137067, 2009).
influenza (continued). "Additionally, SARS-CoV-2 can increase pro-inflammatory cytokines, including interleukin (IL)-2, IL-6, IL-7, and tumor necrosis factor-alpha (TNF-a), to levels not typically seen in bacterial sepsis or influenza and contribute to thrombosis formation via multiple mechanisms." (PMID 38903348, 2024).
Cachexia (422 papers, 1993 to 2026). Severe weight loss, wasting of muscle, loss of appetite, and general debility related to a chronic disease. "Among these were PTHrP, GDF15 and interleukin-6, all of which have been linked to cachexia in various settings." (PMID 41315757, 2026). "In animal models of cachexia, exercise has been shown to attenuate the inflammatory cascade and mitigate weight loss induced by elevated IL-6 concentrations." (PMID 40519290, 2025). "This review identified IL6 as one of four genes linked to key pathways, such as inflammation and metabolism, involved in the development of cachexia." (PMID 39764565, 2025). "Mice receiving viral vector encoding for IL-6 and Activin A demonstrated a phenotype consistent with cachexia, displaying reduced body weight and reductions in skeletal muscle mass." (PMID 41479891, 2025). "Pro-inflammatory cytokines, notably tumor necrosis factor-alpha (TNF-α), interleukin-6 (IL-6), and interleukin-1 beta (IL-1β), significantly contribute to cachexia pathophysiology by promoting muscle wasting and fat loss." (PMID 40133874, 2025). "Among these were PTHrP, GDF15, and IL-6, all of which have been linked to cachexia in various settings 18,19,30,31." (PMID 40964365, 2025). "Elevated IL-6 levels correlate with muscle mass loss and functional decline in both cancer cachexia and age-related sarcopenia, though the overlap with other inflammatory conditions limits specificity." (PMID 41220691, 2025). "In a mice C57BL/6 model of cancer-associated cachexia, increased serum levels of IL-6 were found to correlate with the inset of muscle and adipose waste." (PMID 39683624, 2024). "As expected, the pretreatment indeed also attenuated cachexia, with animals in the anti-IL-6 group showing reduced bodyweight loss, increased food intake, and increased water intake compared with animals in the control group." (PMID 38824130, 2024). "In individuals with lung cancer, Pettersen discovered that the combination of rIL-6R and IL-6 expedited the autophagy of muscle cells through trans-signaling, potentially contributing to muscle loss in patients with cachexia." (PMID 38828409, 2024). "Elevated IL-6 levels are known to be associated with cachexia, and IL-6 inhibitors are used as adjuvants in the treatment of cancer patients to prevent this catabolic effect." (PMID 39596487, 2024). "Together, these experiments demonstrate that reducing IL-6 levels in the brain during cancer progression effectively attenuates cachexia, and also dampens the cancer-associated hyperactivity in the AP network." (PMID 38824130, 2024). "It is believed that sustained elevation of IL-6 production during cancer progression causes brain dysfunctions, which ultimately result in cachexia." (PMID 38824130, 2024). "Previous studies have revealed that IL6-mediated inflammatory pathways are associated with cachexia." (PMID 39703501, 2024). "Third, neutralization of IL-6 in the brain of tumor-bearing mice, via i.c.v. infusion of an IL-6 antibody, attenuates cachexia, counteracts the cachexia-associated hyperactivity in the AP network, and markedly prolongs lifespan." (PMID 38824130, 2024). "Pickled products, such as kimchi, modulate the immune response by regulating the secretion of interleukin-6 (IL-6), which is associated with cachexia in cancer." (PMID 36983811, 2023). "Carnitine also decreased IL-1 and IL-6 serum levels, which are responsible for the progression of cancer-associated cachexia." (PMID 37600065, 2023). "Increased serum levels of interleukin-6 (IL-6) or C-reactive protein (CRP) are observed in cancer-induced cachexia patients, and these cytokines are even used as diagnostic markers for cancer-induced cachexia." (PMID 37240117, 2023). "The principal finding was that high IL-6 was associated with cachexia and a higher risk of immune-related adverse events, while high IL-10 was associated with cachexia and poor overall survival." (PMID 36831513, 2023).
Cachexia (continued). "In conclusion, the M1/M2 macrophage ratio in TME and the immune response mediators released by these cells play a role in CRC-associated cachexia (mainly IL-1 and IL-6)." (PMID 35159388, 2022). "In this work, we focused on the definition of the systemic role of neutrophils in the pathophysiology of cachexia and used in vivo models of cancer that are associated with cachexia in an IL-6-dependent manner." (PMID 35205709, 2022). "Several studies have reported that the overexpression of IL-6 induces muscle loss in various animal models of cachexia." (PMID 36077789, 2022). "The direction of these relationships was also observed by other research and it has been previously suggested that IL‐6 is a central regulator of the progression of cancer and cancer‐associated cachexia." (PMID 35080147, 2022). "For example, proinflammatory cytokines, such as TNF‐α, IL‐1, and IL‐6, promote the activation of transcription factors associated with muscle wasting and play a key role in the pathological mechanism of cachexia." (PMID 36105371, 2022). "The abundance of T-cell populations in spleen is dramatically reduced while cytokines associated to cachexia, such as IL-6, consistently increase in a time-dependent manner starting from 3 days after C26 tumor cells inoculation." (PMID 36158184, 2022). "The majority (11/14) of the studies analysing IL‐6 indicated the presence of a relationship between high levels of IL‐6 and cachexia or weight loss." (PMID 35080147, 2022). "In patients with cancer and in murine models, elevated interleukin-6 (IL-6) has been causally linked to cachexia and altered macronutrient processing." (PMID 35205709, 2022). "In rLIF-driven cachexia mouse models, the mRNA levels of IL-6 increased 50-fold, and in both models, this was associated with anorexia and fat loss." (PMID 35740622, 2022). "The driving role of IL-6 in regulating cachexia was also shown by gain- and loss-of-function experiments in tumor-bearing mice." (PMID 36078078, 2022). "IL-6 is implicated in muscle atrophy associated with cancer-induced cachexia, chronic inflammatory diseases, and immobilization." (PMID 35290243, 2022). "For example, IL-6 plays autocrine roles in supporting tumorigenesis in vivo and induces weight loss and inflammation in cachexia via a paracrine manner." (PMID 36465353, 2022). "Such cytokines can inhibit protein synthesis, resulting in the loss of muscle mass, and IL-6, in particular, is an essential factor in the progression of cancer-related cachexia." (PMID 35054125, 2022). "● Increases IL-6 in tumor and spleen, associated with muscle wasting and systemic inflammation.● IL-6 acts as a poor prognosis marker and a prominent cachexia-associated factor." (PMID 36465353, 2022). "Experimental studies have implicated IL-6 as the main factor in the metabolic changes associated with cancer-related cachexia; IL-6 is also, at least to some extent, responsible for inflammation-related muscle wasting." (PMID 33809200, 2021). "Many studies have focused on the cytokine IL-6 as a mediator of wasting syndromes associated with cachexia 93-96." (PMID 34373744, 2021). "The most important role in CRC-associated cachexia is played by pro-inflammatory cytokines, including the tumor necrosis factor α (TNFα), originally known as cachectin, Interleukin (IL)-1, IL-6, and certain chemokines (e.g., IL-8)." (PMID 33557173, 2021). "In particular, the chronic persistence of systemic IL-6 is associated with several pathophysiological conditions affecting muscle tissue, such as cachexia, aging, insulin resistance, heart failure, and muscular dystrophies." (PMID 34359985, 2021). "In contrast, under pathologic conditions, including muscular dystrophy, cancer associated cachexia, aging, chronic inflammatory diseases, and other pathologies, the plasma levels of IL-6 significantly increase, promoting muscle wasting." (PMID 34359985, 2021).